CTLA4 (cytotoxic T-lymphocyte associated protein 4)
Diseases named in the same sentence as CTLA4 in open-access papers (continued):
Sharing a sentence is not in itself a finding about the gene and the disease.
tumor (continued). "Overall, using both hub-targeted and module-targeted repurposed drugs or biologicals, 4 out of 14 tested drugs showed a clear and significant improvement over anti-CTLA4 alone, while a further 3 displayed a consistent trend of additive anti-tumour effect." (PMID 26193793, 2015). "In murine models of osteosarcoma and colorectal cancer, co-administration of anti-CTLA-4 mAb with either tumor lysate-loaded or immature DCs resulted in tumor growth inhibition, reduced metastasis, and enhanced survival." (PMID 26082780, 2015). "Using a genetic approach that restricts CTLA-4 blockade to anti-tumor T cells, as we propose here, would avoid auto-immune side effects caused by a systemically injected mAb." (PMID 26110267, 2015). "In a glioma model, we have shown that administration of VSV encoding tumor antigens c-Myc, HIF-2α, and Sox-10 in combination with anti-PD-1 therapy or anti-CTLA-4 was able to prolong the survival of mice bearing intra-cranial tumors." (PMID 26580645, 2015). "Although anti-CTLA-4 and anti-PD-1 mAbs demonstrated remarkable anti-tumor activity in advanced CM patients, attaining overall response rates between 40 and 50%, the fact that CR are a few percent indicates that this therapeutic approach needs improvement." (PMID 25859247, 2015). "With the clinical success of CTLA-4 and PD-1 checkpoint blockade in producing long-term responses in several distinct tumor types, there has been growing interest in understanding the specific determinants of host response during immunotherapy." (PMID 25941561, 2015). "The rational of using CTLA-4 blockade in cancer therapy is to release the brake on pre-existing tumor-reactive T cells and to generate new T cell responses." (PMID 26500653, 2015). "Other treatments that impact on different immunomodulatory mechanisms, to induce an immune response against the tumor, have emerged in the last years: anti-PD-1 and anti-CTLA4, BRAF and MEK inhibitors, and others." (PMID 25973756, 2015). "CTLA-4 is a key downregulator of the immune system and blockade of CTLA-4 potentiates the T cell-mediated anti-tumour immune response." (PMID 26334521, 2015). "Engagement of PD-1 or CTLA-4 with ligands expressed on tumor cells or professional antigen presenting cells results in down-regulation of effector T cell function and represents a potent mechanism of immune evasion across a number of human cancers." (PMID 26199729, 2015). "Here, the expression of CTLA-4 was found not only on TILs intercalated within the epithelial component of the tumor but also in the surrounding tumor stroma and at the invasive front of the tumor." (PMID 26605342, 2015). "Therapies targeting PD-1, PD-L1, or CTLA-4 are therefore promising strategies to enhance CTL-mediated anti-tumor efficacy." (PMID 25851535, 2015). "Fluorescent immunostaining demonstrated that more T cells infiltrated into the tumor T1 after local radiation combined with CTLA-4 blockade, whereas only a few T cells were observed to infiltrate into the untreated tumors." (PMID 25980578, 2015). "CTLA-4 is a member of the immunoglobulin superfamily; after T cell activation, CTLA-4 is expressed on the plasma membrane of cells where it acts to inhibit T cell function through a variety of mechanisms, allowing tumor cells to escape immune surveillance." (PMID 26301204, 2015). "In a recent study to develop cancer vaccines, PD-1 and CTLA-4 have shown to be present on tumour infiltrating lymphocytes (TIL), antigen-specific CD8+ T-cells." (PMID 26146643, 2015). "In a comparative study, dual blockade of PD-1 and CTLA-4 restored the dysfunction of these TIL and caused 100% rejection of tumour." (PMID 26146643, 2015). "An especially important finding in these studies was that once mice had experienced a response to CTLA-4 blockade, they were resistant to tumor rechallenge." (PMID 25941561, 2015).
tumor (continued). "Previous studies have shown that the inhibition of PD-1 on CTLA-4 promote tumor regression and prolong survival in both extracranial cancer models and clinical trials." (PMID 26266810, 2015). "Our data in this primary tumor model indicates a synergy between CTLA-4 blockade and Id2-kd N2a cells." (PMID 26079374, 2015). "As Group 1/FCEP Group had the most favorable immunological status (CTLA-4low tumor cells, densityhigh CTLA-4+ lymphocytes, indicative of active immune reaction), their superior prognosis among all patients made sense." (PMID 25893809, 2015). "With the success of CTLA-4 and PD-1 inhibition in clinical trials, significant effort has focused on uncovering other targetable checkpoint pathways active in the tumor microenvironment." (PMID 25941561, 2015). "Preclinical evidence suggests that anti-CTLA-4 antibody can also deplete or inhibit regulatory T cells present in the tumor." (PMID 25682878, 2015). "Given the similarities between adenosine-mediated immune modulation and established checkpoint pathways such as CTLA-4 and PD-1, the application of A2aR blockade to tumor immunotherapy is particularly exciting." (PMID 25941561, 2015). "We subsequently tested irradiated (35 Gray) Id2-kd N2a cells as a whole tumor cell vaccine antigen source in combination with anti-CTLA-4 antibody against AgN2a and found that 60% of mice eradicated established tumors." (PMID 26079374, 2015). "To know if decreased CTLA-4 levels would affect anti-tumor properties of 19-28z+ T cells, we conducted similar experiments in which approximately 50% of the 19-28z+ T cells expressed the anti-CTLA-4 shRNA, comparably to the shRNA transduced 19z1-CD80+ T cells." (PMID 26110267, 2015). "Observations made to date suggest that anti-CTLA-4 antibodies function not only by blocking inhibitory signals from reaching effector T cells but also by depleting regulatory T cells in the tumor microenvironment." (PMID 26161407, 2015). "CTLA4 did appear in the final 44-gene list; CTLA4 expression inducing suppression was reported for tumor-draining lymph nodes, but was also reported for cancer microenvironment." (PMID 26384298, 2015). "In a variety of preclinical tumor models, the administration of an antagonistic anti-CTLA-4 antibody induced tumor rejection." (PMID 25806106, 2015). "Immune checkpoint molecules, such as CTLA-4 and PD-1, act to limit the efficacy of the anti-tumor response by inducing anergy or exhaustion in activated T cells." (PMID 27066495, 2015). "While not improving the clinically used 19-28z CAR, our results demonstrate that CTLA-4 down-regulation can enhance the anti-tumor activity of adoptively transferred human T cells." (PMID 26110267, 2015). "Recent pre-clinical studies highlight the roles of Fcγ receptors (FcγR) and the tumor microenvironment in the activity of different immunomodulatory antibodies, including anti-CTLA-4." (PMID 25859247, 2015). "Combining anti-CTLA-4 and anti-PD-1 with a CSF-1R inhibitor shows profound synergy with a significant reduction in tumor burden." (PMID 26500653, 2015). "We internally validated the relevance of these hubs, within the same tumour model, that modification of these hubs indeed changed the response rate to anti-CTLA4." (PMID 26193793, 2015). "Conversely Tregs increased in patients with a consistent residual disease (TRG 2/3) accompanied by increased tumour infiltration with higher CTLA4 and PD1-Treg." (PMID 25823653, 2015). "Antibodies directed against CTLA-4 and PD-1/PD-L1 pathway have been demonstrated to be effective treatment strategies, which induce durable tumor responses in patients with various malignancies." (PMID 26175922, 2015). "Ipilimumab, a humanised monoclonal antibody to CTLA-4, facilitates stimulation of T-cell activity and potentially enhance anti-tumour responses." (PMID 26371045, 2015). "Although CTLA-4 naturally serves as a peripheral inhibitory signal to prevent over-reactivity of T cells, it also dampens anti-tumor immune responses." (PMID 26350600, 2015).
tumor (continued). "The CTLA-4 focuses on regulating the activation of T cells, while PD-1 regulates effector T-cell activity in peripheral tissues in response to infection or tumor progression." (PMID 26279307, 2015). "Altogether, our results indicate that, upon CD19 recognition, 19-28z+ T cells are activated, expand and efficiently kill the targeted tumor cells while bypassing CTLA-4 inhibition." (PMID 26110267, 2015). "We show here that T cells infiltrating PD-L1 antibody-resistant tumors upregulate additional inhibitory receptors, notably CTLA-4, which impair their ability to mediate tumor rejection." (PMID 25992292, 2015). "This augmented effect of anti-tumor immunity is further enhanced by CTLA-4 blockade, and results in delayed tumor growth." (PMID 26500653, 2015). "Given the impressive results of CTLA-4 and PD-1 inhibition in cancer patients, other checkpoint pathways operating within the tumor environment demand thorough investigation." (PMID 25941561, 2015). "Immune checkpoint blockades, such as CTLA-4 antagonist-antibodies, and multiple cancer vaccines are now invaluable arms of anti-tumor therapy." (PMID 25709607, 2015). "Our previous study and others have demonstrated that systemic blockade of the immunosuppressive CTLA-4 is able to enhance the immune responses against tumor." (PMID 25980578, 2015). "In animal models, it has been shown that CTLA-4 blockade leads to reactivation of the antitumor immune response and tumor shrinkage." (PMID 26161407, 2015). "In this study, we found that CTLA-4 blockade promotes immune infiltration into the tumor microenvironment." (PMID 25992289, 2015). "Like OX40, CTLA-4, and PD-1, T cells express numerous cell surface receptors capable of modulating an anti-tumor immune response." (PMID 25763356, 2015). "They proposed that the release of VEGF-A by the tumor enhances the expression of inhibitory immune checkpoint molecules (PD-1, Tim-3, CTLA-4, and Lag-3) on activated CD8+ T cells in tumors." (PMID 25859247, 2015). "Though a complete review is beyond the scope of this article, investigations of CD73 blockade have shown significant effect on tumor control in mouse models and have also been especially effective in combination with both CTLA-4 inhibition and PD-1 blockade." (PMID 25941561, 2015). "Most important, the tetravalent Del 60 aptamer potentiates protective immunity in mice tumor model with comparable potency to CTLA-4 monoclonal antibody." (PMID 26153774, 2015). "This together with success of CTLA4 blockade indicates that blockade of co-inhibitory pathways has a strong potential for tumour treatment." (PMID 25741704, 2015). "We also note that even though we did not extensively optimize the dosing and scheduling of the repurposed compounds, 7 out of 14 tested drugs that we predicted to work in concert with anti-CTLA4, indeed showed an additional anti-tumour effect." (PMID 26193793, 2015). "The improvement in tumor response with combination CTLA-4 and PD-1 inhibition compared with CTLA-4 inhibition alone was also observed in another randomized double-blind trial." (PMID 27508107, 2015). "Pre-clinical studies combining anti-CTLA-4 and anti-PD-1 have also demonstrated superior anti-tumor control than either of the monotherapies." (PMID 26580645, 2015). "In this sense, in mice concurrently challenged with two tumors, the treatment of one tumor with local RT in combination with the systemic administration of anti-CTLA-4 induced significant growth delay in the second tumor that did not receive local RT." (PMID 24672524, 2014). "Cytotoxic T-lymphocyte-associated antigen 4 (CTLA-4), one of the negative regulators of cytotoxic CD8+ T cells, has been targeted as a means to activate anti-tumor immune CTLs in mouse xenografts." (PMID 24434638, 2014). "Ipilimumab (Yervoy®) is a monoclonal antibody (mAb) designed to block CTLA-4, thereby preventing the development of tolerance and augmenting anti-tumor responses." (PMID 24594636, 2014).
tumor (continued). "CTLA-4 and PD-1 are major T cell regulatory molecules in the second signal of T cell activation that play an important role in tumor immune tolerance." (PMID 25089268, 2014). "Overexpression of FOXP3 and CTLA4 in total BM samples suggests a local accumulation of immunosuppressive Tregs, the MM tumor environment, possibly dampening anti-tumor host immune responses." (PMID 25099367, 2014). "After a T cell recognizes a tumor antigen, signaling through the CTLA-4 pathway prevents the costimulatory signal, and it serves as a natural inhibitory mechanism on the immune response." (PMID 26328216, 2014). "Ipilimumab is a monoclonal antibody that blocks CTLA4 with the aim of promoting anti-tumour immunity." (PMID 25075215, 2014). "CTLA-4 targeted therapy augments endogenous response to tumor cells, thereby leading to tumor cell death when utilized on its own or with other therapeutic interventions." (PMID 25365349, 2014). "Ipilimumab is a monoclonal antibody that blocks cytotoxic T-lymphocyte-associated antigen-4 (CTLA-4), a negative regulator of T-cell activation, thereby augmenting proliferation and infiltration into tumours, leading to tumour cell death." (PMID 24885479, 2014). "Although none of these markers is specifically expressed on Tregs and some of them are also present on activated T cells, recent studies demonstrate the efficacy of anti-CTLA-4 or anti-CCR4 to reactivate immune responses against tumours." (PMID 25050936, 2014). "Anti-CTLA4 mAb treatment has shown robust tumor responses in phase III trials, but with considerable adverse events." (PMID 25774617, 2014). "The CTLA-4 pathway is more important in the early phase of the immune system activation (priming phase), while the PD-1 pathway is more important in the tumor microenvironment during the effector phase." (PMID 25331657, 2014). "To evaluate the 64Cu-DOTA-anti-CTLA-4 mAb uptake by CTLA-4 positive tumor (CT26), we performed PET and ex-vivo biodistribution analysis." (PMID 25365349, 2014). "Both systems are crucial in promoting tumor growth and proliferation: CTLA-4 is competitive for the costimulatory binding CD80/86-CD28 and its binding to CD80/86 generates a negative signal which is responsible for immune cell inactivation." (PMID 25331657, 2014). "There is new evidence that anti-CTLA-4 mAb selectively depletes Tregs in tumor lesions and that this process is dependent on the presence of Fc gamma receptor-positive macrophages." (PMID 24955376, 2014). "Blockade of CTLA-4 with specific monoclonal antibodies can shift the immune system balance toward T-cell activation, leading to tumor rejection." (PMID 25386340, 2014). "Tumor infiltrating lymphocytes can express, in addition to CTLA-4, other immune checkpoint molecules such as PD-1, LAG-3, and TIM-3 among others." (PMID 24883190, 2014). "CTLA-4 blockade broadly enhances immune responses in animal models, including systemic immune hyperactivation and anti-tumor immunity." (PMID 24686897, 2014). "Tumor therapy promises an era of safety in using noninvasive immunomodulatory agents including PD-1-, CTLA-4- and GITR-specific mAbs." (PMID 25105508, 2014). "More specifically, immunotherapy combining 4-1BB activation and CTLA-4 blockade resulted in tumor rejection in 100% of treated animals in a murine RM-1 prostate model." (PMID 25013914, 2014). "The secretion of IFNγ was stimulated to a low extent by treatment of the coculture with tremelimumab, recommend the use of the H-1PV/tremelimumab combination treatment to enhance tumor immunogenicity through both DC activation and CTLA-4 masking." (PMID 24822170, 2014). "An anti-CTLA-4 antibody significantly increased the anti-tumor activity of radiotherapy (TGD was prolonged from 13.1 to 19.5 days), while anti-FR4 and anti-GITR antibodies did not affect efficacy." (PMID 24686897, 2014). "Adding anti–CTLA-4 further increased the potency of this approach, resulting in ~80% tumor rejection of established mammary 4 T1 tumors in mice." (PMID 24855562, 2014).
tumor (continued). "Taken together, these results indicate that iNKT cells can actively suppress the development and/or function of anti-tumor T cells and impair response to anti-CTLA-4 immunotherapy in 4T1 tumor-bearing mice." (PMID 25349699, 2014). "These human studies originated from earlier mouse tumor models, which demonstrate that blockade of CTLA-4-mediated inhibition leads to enhancement of T-cell responses in tumor immunotherapy." (PMID 25538704, 2014). "Treatment with RT and anti-CTLA-4 was effective at controlling the primary irradiated tumor and extending significantly mice survival compared to control (median survival 41 versus 32.5 days, p < 0.05), as previously shown." (PMID 25349699, 2014). "Blocking TREG function by depleting the cytotoxic T-lymphocyte-associated antigen 4 (CTLA-4) appears promising, due to the depletion of TREG from tumor tissues." (PMID 24778636, 2014). "This is in agreement with our results demonstrating that the anti-tumor effect of the anti-CTLA-4 antibody was only observed when it was combined with irradiation." (PMID 24686897, 2014). "Meanwhile, to increase the efficacy of CTLA-4 blockade and detect changes in tumor-specific effector T cells, therapeutic vaccines are being incorporated." (PMID 24904570, 2014). "Second, we developed a molecular imaging probe that targets CTLA-4 and examined its utility in mice bearing CTLA-4-expressing CT26 tumor." (PMID 25365349, 2014). "Antibodies against co-stimulatory molecules, such as 4-1BB (CD137) and Cytotoxic T-Lymphocyte Antigen 4 (CTLA-4, CD152) have the potential to enhance immune responses and produce anti-tumor immunity." (PMID 25013914, 2014). "Ipilimumab blocks the interaction of CTLA-4 with its ligand B7-2, resulting in T-cell activation, proliferation, induction of cytotoxic cytokines, and tumor suppression." (PMID 25374843, 2014). "In preclinical studies of a replication competent adenovirus armed with the coding region of a full length CTLA-4 antibody a 43-fold higher antibody concentration in the tumor as compared to the plasma was noted." (PMID 24605114, 2014). "Recent evidence for the expression of the immunosuppressing molecule CTLA-4 on regulatory T-cells (Tregs) and tumors generated widespread interest in the role of CTLA-4 in tumor escape and peripheral tolerance." (PMID 24822170, 2014). "First, we compared CTLA-4 expression in CT26 tumor tissues, normal colon tissues, and/or cultured CT26 cells by RT-PCR analyses and confirmed that CTLA-4 was strongly expressed in the CT26 tumor tissues compared to the normal colon tissues." (PMID 25365349, 2014). "As both 3M-052 and CpG ODN tend to reduce the level of immune suppression in the tumor microenvironment, their effect on CTLA-4 and TGFβ expression was examined." (PMID 24982761, 2014). "First, RT-PCR was carried out to examine CTLA-4 expression in CT26 tumor tissues and cultured CT26 cells, and the results were compared to those obtained with normal colon tissues." (PMID 25365349, 2014). "In fact, several immunotherapies, such as high-dose IL-2, CTLA-4 blockade and an autologous dendritic cell-based tumor vaccine, have been shown to produce significant benefit to a subset of patients." (PMID 24682539, 2014). "The identification of CTLA-4 expression in tumor prior to molecular targeted therapy would lead to evidence-based and cost-efficient medical care." (PMID 25365349, 2014). "Recent insights into mechanisms of immune regulation and tumour-immune cell interactions have helped to identify checkpoint molecules on immune (CTLA4, PD-1) and tumour (PD-L1) cells as promising therapeutic targets." (PMID 24969320, 2014). "Treatment with focal radiation therapy followed by double immunotherapy with anti-4-1BB and anti-CTLA-4 antibodies significantly extends survival and, more importantly, produces tumor free long-term survival." (PMID 25013914, 2014).